GSTO1 (glutathione S-transferase omega 1)
Diseases named in the same sentence as GSTO1 in open-access papers (continued):
Sharing a sentence is not in itself a finding about the gene and the disease.
vascular dementia (2 papers, 2016 to 2024). A degenerative vascular disorder affecting the brain. "Indeed, in a case/control study, the minor GSTO1*A/A genotype of rs4925 showed elevated frequency in vascular dementia (VaD) patients." (PMID 27259244, 2016).
adenoma (1 paper, 2015). A neoplasm arising from the epithelium. "Compared to healthy tissues that display the highest positivity level (38.79 ± 7.14%), GSTO1 expression gradually and significantly decreases in IBD (26.79 ± 3.42%, P < 0.01), in adenomas (17.70 ± 2.19%, P < 0.001) and in cancer (14.55 ± 1.87%, P < 0.001)." (PMID 26046795, 2015).
alcohol abuse (1 paper, 2025). The use of alcoholic beverages to excess, either on individual occasions ("binge drinking") or as a regular practice. "Environmental risk factors, such as alcohol abuse and cigarette smoking, also exhibited joint effects with GSTO1 and GCLC polymorphisms on the risk of developing psoriasis." (PMID 40278165, 2025). "Furthermore, we observed that environmental risk factors, such as alcohol abuse and cigarette smoking, also exhibited joint effects with GSTO1 and GCLC polymorphisms on the risk of developing psoriasis." (PMID 40278165, 2025). "Moreover, the vast majority of mbmdr G x E models incorporated the combined effects of alcohol abuse and the polymorphisms of the GSTO1 and GCLC genes on the risk of developing the disease." (PMID 40278165, 2025). "This study is the first to demonstrate that polymorphisms in the GSTO1 gene, both individually and in combination with variants of the GCLC gene and alcohol abuse, are associated with an increased risk of psoriasis." (PMID 40278165, 2025).
childhood asthma (1 paper, 2024). "This study uncovers a significant and causal association between GSTO1 and childhood asthma, where increased levels of genetically determined GSTO1 are linked to an elevated risk of developing this condition." (PMID 38730525, 2024). "Elevated levels of seven proteins (TLR4, UBP25, CBR1, Rac GTPase‐activating protein 1 [RGAP1], IL‐21, MICB, and PDE4D) and decreased levels of three proteins (GSTO1, LIRB4 and PIGF) were associated with an increased risk of childhood asthma." (PMID 38730525, 2024). "Based on the genetic data of 4419 (of 4489) plasma proteins from UK Biobank, our study presents compelling evidence linking 10 plasma proteins (GSTO1, LIRB4, PIGF, IL‐21, MICB, PDE4D, RGAP1, TLR4, UBP25 and CBR1) to childhood asthma." (PMID 38730525, 2024).
co-infection (1 paper, 2018). "In the HPV 16/18 co-infection group, the frequencies of GSTO1 genotypes were 19 for AA, 2 for AD, and 0 for DD." (PMID 30115608, 2018).
colitis (1 paper, 2017). Inflammation of the colon. "Since our current experiments have shown that Gsto1 deficient mice have a defect in LPS stimulated inflammation, we evaluated the development of dextran sulfate mediated colitis in Gsto1−/− mice." (PMID 29259211, 2017). "To investigate the role of GSTO1-1 in inflammatory pathways in vivo we have characterized Gsto1 knockout mice and investigated their response to several inflammatory disease models, including inflammatory shock from LPS, dextran sodium sulfate mediated colitis and a pro-inflammatory high fat diet." (PMID 29259211, 2017). "The DSS treated Gsto1−/− mice developed severe transmural acute colitis with extensive mucosal ulceration while the DSS treated wild-type mice developed much less severe acute colitis without ulceration." (PMID 29259211, 2017).
dermatitis (1 paper, 2024). An inflammatory process affecting the skin. "Unexpectedly, a significant relationship between dermatitis and the levels of certain insulin-biosynthesis-and-secretion- or insulin-resistance-related polypeptides (GSTO1, FETUA, GSTP1, IGFALS or LDHA) was observed." (PMID 39062477, 2024).
diabetic nephropathy (1 paper, 2023). "The present study was designed to investigate the possible modifying effect of glutathione transferase polymorphisms (GSTM1, GSTT1, GSTP1 rs1138272/rs1695, GSTO1 rs4925 and GSTO2 rs156697) in the susceptibility to T2DM and diabetic nephropathy." (PMID 36676788, 2023). "Similarly, individuals with the GSTO1*AA genotype rs4925 had higher odds of diabetic nephropathy development compared to the carriers of the wild-type GSTO1*CC genotype, however with borderline significance (OR = 3.81, 95%CI = 0.85–17.09, p = 0.081)." (PMID 36676788, 2023). "Hence, the present study was designed to investigate the possible modifying effect of GSTs polymorphisms (GSTM1, GSTT1, GSTP1, GSTO1 and GSTO2) in the susceptibility to T2DM and diabetic nephropathy as its major microvascular complication." (PMID 36676788, 2023). "The concentration of AGEs in patients without diabetic nephropathy carriers of the GSTO1*AA genotype was 27.36 μg/mL compared to the concentration of 38.42 μg/mL in patients with diabetic nephropathy carriers of the same genotype." (PMID 36676788, 2023).
gastric atrophy (1 paper, 2025). "HP-positive carriers of the GSTO1*A variant allele showed increased risk of developing gastric atrophy and precancerous gastric lesions compared with the reference one (OR = 2.49, 95%CI:1.04–5.96, p = 0.04 and OR = 2.98, 95%CI = 1.21–7.34, p = 0.018, respectively)." (PMID 39859205, 2025). "It is important to note that HP-positive carriers of at least one GSTO1*A variant allele presented an up to three times higher risk of developing gastric atrophy and precancerous gastric lesions (gastric atrophy and/or intestinal metaplasia), compared with the GSTO1*C reference allele." (PMID 39859205, 2025).
gastritis (1 paper, 2025). Inflammation of the stomach. "According to our analysis, the GSTO1 rs4925and GSTO2 rs156697 polymorphisms did not exhibit any influence on the risk of HP-positive gastritis development." (PMID 39859205, 2025). "According to our analysis, the GSTO1 and GSTO2 polymorphisms did not exhibit any influence on the risk of HP-positive gastritis development." (PMID 39859205, 2025).
head and neck squamous cell carcinoma (1 paper, 2025). A squamous cell carcinoma that arises from any of the following anatomic sites: lip and oral cavity, nasal cavity, paranasal sinuses, pharynx, larynx, and salivary glands. "Considering the role of GSTs in detoxification, a study on Thai subjects focused on GSTO1*A140D and GSTO2*N142D polymorphisms in head and neck squamous cell carcinoma (HNSCC) risk." (PMID 40724836, 2025).
Hematuria (1 paper, 2015). The presence of blood in the urine. "Moreover, the GSTO1 CC genotype was found to be associated with a reduced risk of hematuria in patients receiving epirubicin (OR = 0.34, 95% CI = 0.12–0.96)." (PMID 26354850, 2015). "Interestingly, a significant association was found between the GSTP1 rs1695 and GSTO1 rs4925 genotypes and the prevalence of hematuria and irritative voiding symptoms in the epirubicin-treated group." (PMID 26354850, 2015). "In addition, patients with the GSTP1 rs1695 AA genotype had an increased risk of irritative voiding symptoms; while patients with the GSTO1 rs4925 CC genotype had a decreased risk of hematuria." (PMID 26354850, 2015).
hypertrophic cardiomyopathy (1 paper, 2025). A condition in which the myocardium is hypertrophied without an obvious cause. "Proteomic profiling identified a set of six proteins with predictive value for SCD in patients with hypertrophic cardiomyopathy (HCM): thrombospondin-1 (THBS1), complement C3 (C3), aldolase A (ALDOA), Ras suppressor protein 1 (RSU1), glutathione S-transferase omega 1 (GSTO1), and talin-1 (TLN1)." (PMID 40725061, 2025).
ischemia (1 paper, 2009). A hypoperfusion of the BLOOD through an organ or tissue caused by a PATHOLOGIC CONSTRICTION or obstruction of its BLOOD VESSELS, or an absence of BLOOD CIRCULATION. "The proteins encoded by the methylenetetrahydrofolate reductase (MTHFR) and glutathione S-transferase omega-1 (GSTO-1) genes are, through oxidative mechanisms, key participants in the cerebral response to ischemia." (PMID 19624857, 2009).
ischemic stroke (1 paper, 2009). A stroke disorder caused by obstruction of blood flow to the brain, due to thrombotic (local blood clot formation) or embolic (due to a blood clot or other material traveling from another site) event. "We analyzed the C677T polymorphism in the MTHFR gene and the C419A polymorphism in the GSTO-1 gene in 128 patients with non-lacunar ischemic strokes." (PMID 19624857, 2009). "Our study shows no major gene effect of either the MTHFR or GSTO-1 genes as a modifier of ischemic stroke volume." (PMID 19624857, 2009).
memory impairment (1 paper, 2022). "Opposite to the down-regulation of GSTA1, GSTO1, and KEAP1, the BACE1 and MAOA proteins are elevated during the aging-associated memory impairment." (PMID 35767571, 2022).
metastatic disease (1 paper, 2019). "Considering the relevance of investigated signaling pathways in progression of ccRCC, future research directions could be focused on determination of GSTO1 expression in metastatic disease, as well as its potential as a therapy target." (PMID 31861116, 2019).
periodontitis (1 paper, 2024). An acute or chronic inflammatory process that affects the tissues that surround and support the teeth. "Spatial transcriptomics revealed significant upregulation of ACTB, GSTO1, RAB1B, HBB, DMKN, and CTSZ in basal epithelial cells during periodontitis." (PMID 39769019, 2024).
psoriasis (1 paper, 2025). An autoimmune condition characterized by red, well-delineated plaques with silvery scales that are usually on the extensor surfaces and scalp. "The present study demonstrates, for the first time, that polymorphisms in the gene encoding glutathione S-transferase omega 1 serve as novel genetic markers for susceptibility to psoriasis." (PMID 40278165, 2025). "In females, the impact of polymorphisms in the GSTO1 gene on the risk of psoriasis was more pronounced than that of the GCLC gene." (PMID 40278165, 2025). "The present study found that polymorphisms in the GSTO1 gene contribute to susceptibility to psoriasis, with differing effects observed between males and females." (PMID 40278165, 2025). "We conducted an analysis of the relationships between polymorphisms in the GSTO1 gene and the risk of developing psoriasis, examining both the overall population and subgroups stratified by sex." (PMID 40278165, 2025). "The combined influence of polymorphisms in the GSTO1 gene on the risk of developing psoriasis was assessed using haplotype and diplotype analyses." (PMID 40278165, 2025). "Analyses of haplotypes and diplotypes indicated that there were either no significant joint effects or only weak associations between the combinations of GSTO1 genotypes and the risk of developing psoriasis." (PMID 40278165, 2025). "Given that our research is a pilot study, it is essential to conduct further investigations in independent populations to validate the associations identified between GSTO1 gene polymorphisms and the risk of psoriasis." (PMID 40278165, 2025). "The present study revealed an intriguing finding regarding sexual dimorphism in the associations between psoriasis and single nucleotide polymorphisms in the GSTO1 gene, both individually and in combination with GCLC variants and environmental risk factors." (PMID 40278165, 2025). "This investigation is the first to explore the associations between GSTO1 gene polymorphisms and the risk of psoriasis." (PMID 40278165, 2025). "Subsequently, we conducted a replication analysis to investigate the associations between polymorphisms of the GSTO1 gene and susceptibility to psoriasis in the large cohort from the UK Biobank." (PMID 40278165, 2025). "However, we believe that the sexual dimorphism observed in the associations between psoriasis and the SNPs of the GSTO1 and GCLC genes—both individually and in interaction with one another and environmental factors—can be attributed to several reasons." (PMID 40278165, 2025). "Notably, various polymorphisms in the GSTO1 gene exhibited synergistic effects on the risk of psoriasis and contributed to disease susceptibility in a sex-dependent manner." (PMID 40278165, 2025). "The present study is the first to investigate whether polymorphisms in the GSTO1 gene contribute to the risk of developing psoriasis." (PMID 40278165, 2025). "Therefore, the present pilot study aimed to determine whether common single nucleotide polymorphisms (SNPs) in the GSTO1 gene are associated with the risk of psoriasis." (PMID 40278165, 2025). "Gaining deeper insights into how the polymorphisms of the GSTO1 gene interact with other genes associated with glutathione metabolism could pave the way for innovative, evidence-based strategies for treating and preventing psoriasis." (PMID 40278165, 2025). "Although the associations of psoriasis with the rs11191736 and rs187304410 polymorphisms could not be replicated in the overall population of the UK Biobank, 40 other SNPs in the GSTO1 gene have been identified as nominally associated with the risk of psoriasis." (PMID 40278165, 2025). "However, no studies to date have been conducted to investigate whether polymorphisms in the gene encoding glutathione S-transferase omega 1 (GSTO1) contribute to susceptibility to psoriasis." (PMID 40278165, 2025).
psoriasis (continued). "The application of the mbmdr methods enabled the identification of epistatic interactions between the polymorphisms of the GSTO1 gene and variants of GCLC in determining the risk of psoriasis." (PMID 40278165, 2025). "The present study is the first to demonstrate that polymorphisms in the GSTO1 gene, both individually and in combination with GCLC polymorphisms and glutathione-depleting environmental risk factors, contribute to susceptibility to psoriasis." (PMID 40278165, 2025). "Another possible explanation for the sexual dimorphism observed in the associations between GSTO1 and GCLC polymorphisms and psoriasis is that women generally exhibit greater sensitivity to the toxic effects of chemical pollutants compared to men, as evidenced by some studies." (PMID 40278165, 2025).
seminoma (1 paper, 2023). A radiosensitive malignant germ cell tumor found in the testis (especially undescended), and extragonadal sites (anterior mediastinum and pineal gland). "Due to the biological origin and the clinically distinctive characteristics of the two large categories of testicular GCT, the individual effect of GSTO1*C419A (rs4925), GSTO2*A424G (rs156697), and GSTO2*A183G (rs2297235) polymorphisms on the risk for seminoma development was estimated as well." (PMID 37374052, 2023).
Sepsis (1 paper, 2025). Sepsis is defined as life-threatening organ dysfunction caused by a dysregulated host response to infection. "MR analysis suggested that a decrease in GSTO1 levels is associated with an increased risk of sepsis, and that sepsis influences the levels of S100A9, TXN, and GSTO1." (PMID 40108736, 2025). "Lower GSTO1 levels were associated with a higher risk of sepsis (OR = 0.93, 95%CI: 0.87–0.99, P = 0.034)." (PMID 40108736, 2025). "Through bioinformatics approaches, this study successfully identified five genes (IRAK3, S100A9, TXN, NFATC2, and GSTO1) associated with programmed cell death in the context of sepsis." (PMID 40108736, 2025). "This study provides a new method for revealing the regulatory mechanism of host response in sepsis, improving the diagnosis and treatment of patients with sepsis, and suggests that GSTO1 with bidirectional causal association may be an important marker in the progression of sepsis." (PMID 40108736, 2025). "In addition, from the genetic perspective of Mendelian randomization analysis, GSTO1 with bidirectional causal association may be an important marker of sepsis." (PMID 40108736, 2025). "It has also been proved that sepsis affects the levels of S100A9, TXN and GSTO1 from the perspective of genetics, but the underlying mechanism is still unclear and needs to be further verified by basic experiments." (PMID 40108736, 2025). "GSTO1 was also expressed in a variety of cell types, and the expression of GSTO1 in T cells, B cells and NK cells in the sepsis group was higher than that in the control group." (PMID 40108736, 2025). "The results showed that the expression of IRAK3, S100A9, TXN and GSTO1 in the sepsis group was increased, while the expression of NFATC2 in the sepsis group was decreased (P < 0.05)." (PMID 40108736, 2025). "A proteomic study showed that GSTO1 is mainly expressed in macrophages, widely involved in inflammatory and immune responses, and highly expressed in septic plasma, which is a potential research target for sepsis, but needs to be confirmed by more samples." (PMID 40108736, 2025). "In order to verify the validity of the diagnostic marker genes, a KS test was performed on the GSE69063 dataset for these five genes, and the results showed that IRAK3, S100A9, TXN and GSTO1 were up-regulated in the sepsis group, while NFATC2 was down-regulated." (PMID 40108736, 2025). "Finally, GWAS data were relatively limited and MR Analysis could not be performed to assess whether there is a nonlinear relationship between sepsis and S100A9, TXN and GSTO1 levels." (PMID 40108736, 2025).
steatosis (1 paper, 2021). Increased lipid within the cytoplasm of cells. "A total of two genes were common in two out of four datasets (MTR and GSTO1), but no gene was differentially expressed between HC and steatosis in all datasets." (PMID 34869521, 2021).
Zinc deficiency (1 paper, 2024). A deficiency of the essential metal Zinc; an essential cofactor for many enzymes. "Compared to serum zinc, serum glutathione sulfotransferase omega-1 (GSTO1) responds better to zinc supplementation and has a higher correlation coefficient with zinc intake, making it promising for the diagnosis of zinc deficiency." (PMID 39221327, 2024).